ADSL (adenylosuccinate lyase)
Diseases named in the same sentence as ADSL in open-access papers (continued):
Sharing a sentence is not in itself a finding about the gene and the disease.
Lissencephaly (2 papers, 2015 to 2020). A spectrum of malformations of cortical development caused by insufficient neuronal migration that subsumes the terms agyria, pachygyria and subcortical band heterotopia. "Deficiency of ADSL in humans causes atrophy of distinct regions of the brain, including the cerebral cortex, in addition to hypomyelination and lissencephaly." (PMID 32344379, 2020). "The finding of atrophy of the cerebral cortex, corpus callosum, cerebellar vermis, lack of/or delayed myelination, anomalies of the white matter or lissencephaly on MRI examination should alert neonatologists and radiologists to the possibility of ADSL deficiency." (PMID 25112391, 2015).
AICAribosiduria (1 paper, 2022). "The ADSL reverse reaction is highly activated in ATIC KO cells that naturally accumulate AICAR, and most probably also in the cells of AICAribosiduria patients." (PMID 36557247, 2022).
Ataxia (1 paper, 2019). Ataxia refers to impaired coordination of voluntary muscle movement. "Methyltetrahydrofolate reductase (MTHFR) deficiency and adenylosuccinate lyase deficiency have been reported as presenting with learning disability, ataxia, seizures, autistic features and excessive laughter." (PMID 31235867, 2019).
brain tumors (1 paper, 2020). "Overexpression of PPAT and ADSL is associated with poor survival of patients with brain tumors." (PMID 32218208, 2020). "The knockdown of ADSL, GMPS, and PRPS1 decreases brain tumor initiating cell maintenance in both immunodeficient and immunocompetent mouse models." (PMID 32218208, 2020).
cardiac hypertrophy (1 paper, 2025). "In summary, gain-of-function mutations in Notch2 gene induce cardiac hypertrophy and diastolic dysfunction by disrupting ADSL-mediated AMP biosynthesis, and targeting purine nucleotide metabolism may represent an attractive therapeutic strategy for the treatment of cardiac diseases." (PMID 40104444, 2025).
ciliopathy (1 paper, 2022). A genetic disorder of the cellular cilia or the cilia anchoring structures, the basal bodies, or of ciliary function. "If ADSL deficiency would be less severe or only a subset of tissues would be affected, patients may not present classic and widespread ciliopathy features." (PMID 35133277, 2022).
colorectal tumor (1 paper, 2021). "Of note, ADSL levels are already lower in normal cells compared to colorectal tumor cells." (PMID 33754045, 2021).
Dihydropyrimidinase deficiency (1 paper, 2021). "Seizures can occur in purine and pyrimidine metabolic disorders including Lesch-Nyhan syndrome, adenylosuccinate lyase (ADSL) deficiency, dihydropyrimidine dehydrogenase deficiency, and dihydropyrimidinase deficiency." (PMID 34295297, 2021).
Dystonia (1 paper, 2025). An abnormally increased muscular tone that causes fixed abnormal postures. "The hypothesis is supported by the finding that loss‐of‐function variants in ADSL, which is responsible for the conversion of IMP into adenine nucleotides, and have been implicated in a neurodevelopmental disorder that can manifest with dystonia." (PMID 40026236, 2025).
endometrioid carcinoma (1 paper, 2024). "Evidence confirms that in human endometrioid carcinoma, ADSL expression was correlated with increased histological aggressiveness and the extent of primary tumor progression." (PMID 38433141, 2024).
folate deficiency (1 paper, 2020). A nutritional condition produced by a deficiency of FOLIC ACID in the diet. "We also found that BH4 de-novo synthesis is blocked in both the ADSL knockout and folate deficiency model." (PMID 32384607, 2020). "We found a high similarity between folate deficiency and ADSL deficiency in terms of blocked metabolites." (PMID 32384607, 2020). "Based on our results, we postulated the hypothesis that the ATP pool is reduced, since the neurons divide during a critical developmental period and cannot be fully replenished due to ADSL deficiency or folate deficiency." (PMID 32384607, 2020). "Our study confirmed this finding using an entirely different approach and proposes a more detailed mechanism to explain how purine deficiency, caused by ADSL or folate deficiency, can lead to the depletion of ATP and subsequently to the impairment of DNA methylation during cell division." (PMID 32384607, 2020). "The fact that folate deficiency and ADSL (and possibly also ATIC) deficiency both result in symptoms similar to ASD and, at the same time, exhibit very similar blocked metabolite sets, suggests a possible common pathophysiological mechanism that could lead to the development of ASD." (PMID 32384607, 2020).
Granuloma (1 paper, 2020). A compact, organized collection of mature mononuclear phagocytes, which may be but is not necessarily accompanied by accessory features such as necrosis. "Regarding the counts of granulomas in the liver tissue, the reductions of the NDPK and ADSL groups in relation to the INF group reached 45.83% and 32.55%, respectively." (PMID 33072110, 2020).
insulinoma (1 paper, 2020). "Prior work has shown the inhibition of ADSL in an insulinoma cell line lowered S-AMP, an insulin secretagogue, to impair glucose-stimulated insulin secretion." (PMID 32589682, 2020).
liver fibrosis (1 paper, 2023). "The same response profile was observed in the study that tested the enzymes NDPK, ADSL and MIX in mice as immunizing agents, showing that the purine salvage pathway enzymes of S. mansoni interfere with the reduction of liver fibrosis." (PMID 37111413, 2023).
lymph node metastasis (1 paper, 2025). "ADSL, ADCY3, and NME6 were associated with lymph node metastasis, distant metastasis, and differentiation, whereas APRT and NME3 were independent of these clinical variables." (PMID 40017120, 2025). "The results indicated that lymph node metastasis and distant metastasis were independent predictors of ADSL expression (lymph node metastasis: OR = 0.70; 95% CI: 0.49–0.99; P = 0.046; distant metastasis: OR = 0.48; 95% CI: 0.28–0.81; P = 0.007)." (PMID 40017120, 2025).
malaria (1 paper, 2024). Malaria is a serious and sometimes fatal disease caused by a parasite that commonly infects a certain type of mosquito which feeds on humans. "Phylogenetic studies of the genus Plasmodium have been performed using the sequences of the nuclear, mitochondrial and plastid genes as well as the adenylosuccinate lyase (ASL) gene that encodes an enzyme involved in the salvage of host purines needed by malaria parasites for their DNA synthesis." (PMID 38820542, 2024).
melanoma (1 paper, 2023). A malignant, usually aggressive tumor composed of atypical, neoplastic melanocytes. "In future projects, we plan to develop DTIC-resistant melanoma cell lines and elucidate the mechanisms underlying the regulatory roles of ADSL and Dicer in DTIC resistance." (PMID 37976135, 2023). "The analysis of patient data from TCGA data set further revealed that Dicer expression is positively associated with ADSL expression; consistent results were observed in the tissue microarrays of patients with melanoma." (PMID 37976135, 2023). "IHC staining further confirmed lower ADSL expression levels in melanoma tissues than in normal skin tissues." (PMID 37976135, 2023). "These clinical findings indicate that Dicer is strongly correlated with ADSL expression and survival outcomes in melanoma." (PMID 37976135, 2023). "First, we established melanoma cell lines with stable ADSL silencing; gene silencing was confirmed through Western blotting." (PMID 37976135, 2023). "We discovered that DTIC treatment enhanced ADSL expression and that Dicer silencing significantly reduced ADSL expression in melanoma cells." (PMID 37976135, 2023). "This prompted us to investigate the role of Dicer-mediated ADSL in the DTIC sensitivity of melanoma cells." (PMID 37976135, 2023). "Furthermore, the silencing of ADSL expression was observed to reduce the sensitivity of melanoma cells to DTIC." (PMID 37976135, 2023). "Notably, the level of ADSL expression was found to be high in early-stage melanoma tissues and low in late-stage melanoma tissues." (PMID 37976135, 2023). "Furthermore, Dicer silencing leads to DTIC resistance and an increase in cancer stemness in melanoma cells by suppressing the downstream expression of ADSL." (PMID 37976135, 2023). "We found that DTIC significantly affected the expression levels of various metabolic enzymes, including ADSL, PYCR1, PRODH, and FTH1, in melanoma cells." (PMID 37976135, 2023). "Consequently, investigation of the relationship between Dicer-mediated ADSL dysregulation and DTIC resistance in melanoma is imperative." (PMID 37976135, 2023). "We further assessed ADSL expression using patient data obtained from TCGA database and found considerably lower levels of ADSL expression in melanoma tissues than in nonmelanoma tissues (depending on the tumor stage)." (PMID 37976135, 2023). "On the basis of these findings, we surmise that Dicer regulates ADSL expression (but ADSL does not regulate Dicer expression), thus influencing DTIC sensitivity in melanoma cells." (PMID 37976135, 2023).
neonatal encephalopathy (1 paper, 2024). "Regarding ADSL, several point mutations have been identified in over 100 cases with varying severity (ranging from fatal neonatal encephalopathy to mild or severe neuronopathic disorders), depending on the ratio of accumulated dephosphorylated SAICAR and AdS." (PMID 38444943, 2024). "In the case of ADSL mutation linked to fatal neonatal encephalopathy, no signal for the mutated enzyme was detected in the fibroblasts." (PMID 38444943, 2024).
purine metabolic disorders (1 paper, 2023). "We have extended the C. elegans model of adenylosuccinate lyase deficiency to include analysis of neurobehavioral phenotypes, which are a largely mysterious aspect of purine metabolic disorders." (PMID 37773959, 2023).
schistosomiasis (1 paper, 2020). An infectious disease caused by parasitic trematodes of the genus Schistosoma that colonize human blood vessels and release eggs that can cause granulomatous reactions leading to acute (swimmer's itch or acute schistosomiasis syndrome) or chronic disease. "Our results indicate that the recombinant proteins NDPK and ADSL from the purine salvage pathway of S. mansoni have the potential for a possible formulation of a vaccine against mansonic schistosomiasis." (PMID 33072110, 2020).
Seckel syndrome (1 paper, 2022). A rare autosomal recessive inherited syndrome caused by mutations in the ATR gene, RBBP8 gene, CENPJ gene, CEP152 gene, CEP63 gene, NIN gene, DNA2 gene, or TRAIP gene. "This indicated that the reduced cellularity caused by ADSL depletion occurs in a manner mechanistically distinct from Seckel syndrome driven by ATR deficiency or centrosome duplication defects." (PMID 35133277, 2022).
status epilepticus (1 paper, 2015). Status epilepticus is defined as a continuous seizure lasting more than 30 min, or two or more seizures without full recovery of consciousness between any of them. "General and emergency care pediatricians must consider ADSL deficiency in parallel with status epilepticus." (PMID 25112391, 2015). "Corresponding to the clinical diversity, the epileptic phenotypes associated with ADSL deficiency are also highly variable, comprising myoclonus, partial seizures, infantile spasms, and status epilepticus." (PMID 25112391, 2015).
thymoma (1 paper, 2022). A neoplasm arising from the epithelial cells of the thymus. "Since ADSL is a known oncogenic driver in several cancers and a potential predictive biomarker for response to the purine antimetabolite, 6-mercaptopurine in preclinical models, a more in-depth analysis of ADSL, especially in B2 and B3 thymomas appears warranted under a therapeutic perspective." (PMID 35326714, 2022). "Interestingly, ADSL one of the enzymes involved in purinosome complex formation and de novo purine synthesis showed high expression in our cohort of B2 and B3 thymomas but not in TCs." (PMID 35326714, 2022).
West syndrome (1 paper, 2018).
tumor (13 papers, 2018 to 2025). "qRT-PCR validation showed up-regulation of PNPLA3 and SARDH, and down-regulation of ADSL, in tumor tissues." (PMID 40313243, 2025). "Recent research has found that fumaric acid produced by ADSL also plays a role in promoting tumour growth in GBM." (PMID 40313243, 2025). "In contrast, the expression levels of PNPLA3 and SARDH were significantly elevated in the tumor group compared to the control group, while ADSL expression was notably reduced in tumor tissues." (PMID 40313243, 2025). "Their findings indicated that ADSL enhances tumor cell proliferation, invasion, and migration by modulating KLRC3 expression." (PMID 38433141, 2024). "Several investigations have reported reduced adenylosuccinate lyase levels in various neoplasias, such as transplanted tumors, transformed cell lines, and human tumors." (PMID 38433141, 2024). "In our study, we firstly checked the gene expression of ADSL in the normal, tumor and metastasis PCa in all the available datasets." (PMID 34488772, 2021). "In accordance with our results obtained in vitro, treatment with 6-MP significantly reduced tumor volume only upon ADSL overexpression." (PMID 33754045, 2021). "Consistent with the phenotype observed with primary tumor growth, ADSL depletion diminished tumor cell colonization in the lung, even though the starting amount of injected cells was comparable." (PMID 31729379, 2019). "Despite the variation between different normal and tumor samples, likely reflecting patient tissue heterogeneity, ADSL was upregulated in tumors compared with their adjacent normal tissue." (PMID 31729379, 2019). "The analysis of ATIC and ADSL protein expression through immunohistochemistry showed much more intense expression in tumor than in healthy tissue for AC and SCC cases." (PMID 30099851, 2018). "In addition, qRT -PCR validation revealed significant differences in the expression of PNPLA3, SARDH, and ADSL in the control and tumour groups." (PMID 40313243, 2025). "Additionally, ADSL expression increased tumor growth in vivo and sensitized CRCs to 6-MP in vitro, ex vivo (PDOs) and in vivo (CAM model)." (PMID 33754045, 2021). "In this sense, other groups have described the deficiency of ADSL and ATIC as affecting the formation and assembly of purinosome, and there is evidence that both enzymes are key in the regulation of the synthesis pathway of purines during tumor development." (PMID 30099851, 2018). "However, additional studies using a broader range of cell lines, including primary tumor cell lines with BRAF variants, are needed to determine whether Dicer-mediated ADSL expression exerts a similar effect on these cells." (PMID 37976135, 2023). "When collecting the clinical features (Gleason score, PSA level and tumor stage) and survival data, we excitedly found that high ADSL gene expression might shorten the time of metastasis-free survival (HR = 1.68 (1.12–2.52), P = 0.012) and biochemical recurrence (HR = 1.57 (1.04–2.37), P = 0.003)." (PMID 34488772, 2021). "The results showed that the expression levels of ADK, ADSL, ATIC, DPYS, ENTPD2, TXNRD1, and UCK2 in at least one tumor cell line were consistent with the predictions." (PMID 37999212, 2023). "SMS can influence the metabolic process and is involved in tumor growth.Overexpression of ACACA, ME1, ADSL or S100A10 promotes HCC growth, migration or invasion, and is connected with poor prognosis." (PMID 36632140, 2023). "By modulating the expression levels of ADSL in vitro, we showed that ADSL promotes proliferation and migration in CRC cells, as well as tumor growth in vivo in the CAM model." (PMID 33754045, 2021). "Supporting these results, we also found an overexpression of ADSL, the enzyme in charge of AMP synthesis, both at a genetic and at a protein level in tumor tissue for AC and SCC cases." (PMID 30099851, 2018).
tumor (continued). "Additionally, along the aggression of PCa, ADSL expression also presented the visibly rising trend (Gleason score: P = 0.003; PSA level: P = 0.010; tumor stage: P = 0.001)." (PMID 34488772, 2021). "Our results suggest that ADSL is overexpressed in CRC but its expression is not increased upon tumor progression." (PMID 33754045, 2021). "Immunoscore results showed that ADSL expression was significantly increased in tumor tissues compared to non-tumor tissue areas (p = 0.001)." (PMID 33754045, 2021). "To determine whether modulating ADSL expression levels would also affect response to 6-MP in vivo, we pre-treated ADSL-overexpressing Caco-2 cells with 6-MP for 24 h before implantation in the CAM and then screened for tumor formation." (PMID 33754045, 2021). "In the first TMA, after excluding the samples with missing tissue core or poor staining, 73 tumor samples and 13 non-tumoral tissue cores were analyzed for ADSL protein expression." (PMID 33754045, 2021). "To further demonstrate the putative oncogenic role of ADSL in CRC, we modulated ADSL expression and xeno-transplanted ADSL-overexpressing or control CRC cells into the chicken chorioallantoic membrane (CAM) to assess tumor growth in vivo." (PMID 33754045, 2021). "Overtime, differently from control cells, ADSL-depleted tumor cells failed to grow, which was reflected by the decreased tumor size and weight at necropsy." (PMID 31729379, 2019). "Although it is unclear whether ADSL levels are genuinely reduced in advanced-stage CRCs, our results suggest that ADSL plays an oncogenic role in CRC initiation rather than tumor progression, which would be consistent with the upregulated ADSL activity in colon pre-neoplastic lesions." (PMID 33754045, 2021). "ADSL gene knock-down did not significantly impact the viability of NCM460 cells, suggesting that while it confers a proliferative advantage to tumor cells, it does not have the same effect/impact in normal colonic cells." (PMID 33754045, 2021).